HIF1A (hypoxia inducible factor 1 subunit alpha)
Diseases named in the same sentence as HIF1A in open-access papers (continued):
Sharing a sentence is not in itself a finding about the gene and the disease.
cancer (continued). "In RCC, HIF1α reprograms the metabolism of cancer cells, in part by increasing the glucose uptake, and in part by controlling the glucose flux through the glycolytic and pentose phosphate pathways." (PMID 25945836, 2015). "For example, WW domain-containing oxidoreductase (WWOX), as a modulator of cancer metabolism, via its first WW domain, physically interacts with HIF1α and modulates its levels and transactivation function." (PMID 25685782, 2015). "Subsequently, several other miRNAs including miR-20b, -22, -138, -155, -199a-5p -429 and -519c were also shown to regulate HIF-1a in cancer or hypoxic conditions." (PMID 26030758, 2015). "There are several reports that addition of AA to cancer cell lines decreases the amount of HIF-1α protein and also inhibits HIF activity." (PMID 26547841, 2015). "In the OVCAR-3 cancer cell line, the protein expression levels of HIF-1α were significantly decreased (P<0.05) upon the administration of higher concentrations of GA." (PMID 25663929, 2015). "Collectively, the present study demonstrates a mechanical cascade of BRMS1 suppressing cancer cell invasion through downregulating HIF-1α transcript and consequently reducing Snail and TWIST1 expression." (PMID 26520789, 2015). "Whereas our study showed that in ESCC, SOX2 exerted a regulatory action upstream of STAT3/HIF-1α, another report indicated the action of SOX2 downstream of HIF-1α in cancer cells other than ESCC." (PMID 26370982, 2015). "Under hypoxic conditions they reduced the expression of HIF-1α in various cancer cells by inhibiting the PI3K/AKT/mTOR pathway." (PMID 26006245, 2015). "As a step towards understanding the complexity of cancer biology, we employed intermittent induction of HIF-1α and HIF-2α in various cancer cell types and investigated their differential effects on malignant progression in immunodeficient mice." (PMID 25893706, 2015). "It is well recognized that hypoxia-inducible factor 1 alpha (HIF-1α) is involved in cancer metastasis, chemotherapy and poor prognosis." (PMID 26057751, 2015). "For example, it was reported that HIF-1α expression inversely correlates with Sp1 binding to the CDKN1A promoter region in cancer cells." (PMID 26703734, 2015). "Our finding that CDCA, guggulsterone reduced amount of HIF-1α protein suggests that these can alleviate the hepatic fibrosis and cancer which are enhanced by HIF-1α." (PMID 26098428, 2015). "It has been shown that HIF1α is involved in hypoxic adaptation and angiogenesis during cancer progression." (PMID 26205124, 2015). "The top over-represented canonical signaling pathways included modulation in commonly observed “Cancer” signatures, such as the regulation of matrix metalloproteases, cancer metastasis signaling, HIF1α signaling, and HER-2 signaling." (PMID 26503699, 2015). "For both types of cells, the accumulation of HIF-2α protein was relatively slower than the accumulation of HIF-1α, as it has been seen for cancer cells." (PMID 25830774, 2015). "Combination cancer therapies that target cancer metabolism via modulation of HIF-1α are attractive due to the central role HIF-1α plays in cancer metabolism and drug resistance." (PMID 25888489, 2015). "In this study, we explored if the HIF-1α-VEGF secretion axis was involved in metformin-induced angiogenic abrogation of cancer cells with highly phosphorylated HER2." (PMID 26625311, 2015). "Inversely, HIF-1α-VEGF signaling was highly activated in cancer cell lines (MDA-MB-453, SKBR3 and 4T1) with highly phosphorylated HER2 protein." (PMID 26625311, 2015). "RNA interference-mediated inhibition of HIF-1α expression induced by the iron-depriving agent desferrioxamine increases Sp1 binding to the CDKN1A promoter region in cancer cells." (PMID 26703734, 2015).
cancer (continued). "G-quadruplexes have been shown to be present in regions of biological significance, such as human telomeres and in the promoter regions of several cancer-linked genes, including c-myc, bcl-2, c-kit, VEGF, Ras, HIF-1α, and Rb41,42." (PMID 25449683, 2015). "The present study investigated the effects of bortezomib on HIF-2 activity in cancer cells with different levels of HIF-1α and HIF-2α subunits." (PMID 26622817, 2015). "HIF-1α supports cancer progression, metastasis, and chemoradiation resistance mainly through the induction of proangiogenic, survival promoting, and proinflammatory factors that cause chronic inflammation." (PMID 26229239, 2015). "Conversely, in cancer cells exposed to hypoxia, pyruvate is shunted away from the mitochondria, whereby HIF-1α upregulates the expression of PDK1 to inhibit the PDH activity." (PMID 26339797, 2015). "We found lactate secreted by cancer cells promote the synthesis of PGE2 of THP-1 monocytes through stabilizing hypoxia-inducible factor 1α (HIF-1α) in normoxia." (PMID 25938544, 2015). "HIF1α represents one of the principal regulators of metabolism and energetic balance in cancer cells through its regulation of glycolysis, glycogen synthesis, Krebs cycle and the pentose phosphate shunt." (PMID 25605240, 2015). "NFκB24, 31 and NFAT32 have been shown to increase HIF1A mRNA expression, however their relative roles in regulating HIF1A transcription in the cancer context remain to be fully elucidated." (PMID 26647819, 2015). "Thus, HIF1A could be a useful prognostic marker for cancers early predisposition." (PMID 26715988, 2015). "Hypoxia-inducible factor-1α (HIF-1α) is a well validated target protein found in various malignant tumors." (PMID 26378810, 2015). "The abundance of HIF-1α as well as HIF-2α is frequently detected in the vast majority of human cancers." (PMID 25893706, 2015). "We assessed the ERK1/2 and Akt pathways, which are up-regulated frequently in other cancers, through HIF-1α activity and found that the phosphorylation levels of ERK1/2 and Akt decreased, whereas ERK1/2 and Akt proteins were unchanged." (PMID 26228921, 2015). "Aberrant overexpression of HIF1α in many different cancers has led to intensive efforts to develop HIF1α-targeted therapies." (PMID 26183215, 2015). "The result together showed that the increased activity of NF-κB in UXT overexpressing cancer cells induced glycolysis via upregulation of HIF-1α." (PMID 25974965, 2015). "HIF-1α is overexpressed in various cancers and therefore represents a considerable chemotherapeutic target." (PMID 26610526, 2015). "Taken together with the regulation of HIF1α expression that we have reported previously, Cezanne appears to be an attractive new drug target in the treatment of cancer." (PMID 26148512, 2015). "Salternamide A was identified for the first time as an inhibitor of HIF-1α accumulation under hypoxic conditions in cancer cells." (PMID 26610526, 2015). "Recent studies indicate that MIF leads to HIF-1α activation under hypoxic conditions leading to enhancement of cancer growth and metastasis." (PMID 26530123, 2015). "We previously identified SphK1 as a modulator of HIF-1α as a key mediator of the adaptive response to hypoxia in multiple cancer cell models." (PMID 25915662, 2015). "In one of these studies, HIF-1α was shown to be a central determinant of TN cancer stem-like cell chemo-resistance." (PMID 26141457, 2015). "Inhibition of CK1δ increases lipid droplet formation and proliferation of both cancer and normal cells specifically under hypoxia and in an HIF-1α- and lipin-1-dependent manner." (PMID 25744540, 2015). "Because HIF-1α is overexpressed in different human cancers and their metastases, the inhibition of the HIF-1 pathway represents a promising approach in cancer therapy." (PMID 25685782, 2015). "MIF is a direct target of HIF1α and is described as a link between inflammation and cancer, contributing to a microenvironment favouring cancer progression." (PMID 26183215, 2015).
cancer (continued). "In human cancers, HIF-1α is overexpressed as a result of intratumoral hypoxia and of genetic alterations affecting crucial oncogenes and tumor suppressor genes." (PMID 25733977, 2015). "We previously observed that the aminobisphosphonate zoledronic acid inhibits the activity of hypoxia inducible factor-1α (HIF-1α), a master regulator of cancer cell metabolism." (PMID 26372812, 2015). "We focused our interest on DEC1 (BHLHE40/STRA13/SHARP-2), a transcriptional repressor under the control of HIF-1α, already demonstrated to be involved in cancer aggressiveness and motility." (PMID 26183399, 2015). "Previous studies found that HIF-1α can bind to the HRE of the miR-210 gene to activate miR-210 transcription in a variety of cancer types." (PMID 26254226, 2015). "PX-478 inhibits HIF-1α at protein levels and transactivation in a variety of cancer cell lines by decreasing levels of HIF-1α mRNA and inhibiting translation." (PMID 26640316, 2015). "Metabolic regulators such as HIF-1α, and PDHKII have been implicated not only in cancer but also in induced pluripotency, so we wondered if this type of regulatory network is also present in ESCs." (PMID 26147621, 2015). "Additional support for targeting HIF1α to combat cancer is based on observations that anti-angiogenic therapies, while initially beneficial, will ultimately induce the expression of HIF1α." (PMID 26501324, 2015). "Our results of protein expression screening showed a high level of HIF-1α accumulation in HER2+ cancer cells, which were accompanied by high VEGF expression." (PMID 26625311, 2015). "HIF-1α is upregulated in various types of human malignant tumors including brain, cervical, pancreatic, liver, gastric, bladder, breast, and ovarian cancers." (PMID 26378810, 2015). "Next, we examined the effects of serum depletion on the gene expression of SPC, AQP5, and also hypoxia-inducible factor-1α (HIF-1α) which regulates the phenotypes of cancer cells including their progressive proliferation." (PMID 26167183, 2015). "HIF-1α is a major regulator of cancer metabolism, particularly glycolysis, glycogen synthesis, TCA cycle, flux into the PPP shunt, nucleotides, amino acids and leptin metabolism." (PMID 25605240, 2015). "PX-478 (S-2-amino-3-[4V-N,N,-bis(2-chloroethyl) amino]-phenyl propionic acid N-oxide dihydrochloride) is a specific agent that suppresses constitutive and hypoxia-induced levels of HIF-1α in cancer cells." (PMID 25544770, 2015). "Treatment of cancer cells with this antibiotic augments Sp1 activity under normoxia, resulting in elevation of HIF1A transcript levels, potentially by increasing binding activity rather than by increasing the protein level." (PMID 26703734, 2015). "In the present study, we demonstrate that SA efficiently inhibits the hypoxia-induced accumulation of HIF-1α in a time- and concentration-dependent manner in various human cancer cells." (PMID 26610526, 2015). "While it is largely accepted that HIF1α is the more tumorigenic isoform in most types of cancer, some researchers have suggested that HIF2α is more tumorigenic than HIF1α in ccRCC." (PMID 25830305, 2015). "This characteristic is originally illustrated by the Warburg phenotype, which corresponds to the HIF-1α-dependent switch from oxidative to glycolytic metabolism allowing cancer cells to survive with reduced O2 availability." (PMID 26713093, 2015). "Hypoxia inducible factor 1, alpha subunit (HIF1A) was downregulated in common in cancer cells, while stromelysin-1 (matrix metallopeptidase 3), vascular endothelial growth factor A (VEGF-A), and neuropilin-1 were upregulated in common in fibroblasts." (PMID 26171396, 2015). "We previously reported that cetuximab, an EGFR-blocking antibody, inhibits cancer metabolism via downregulation of HIF-1α and reverses the Warburg effect in cancer cells." (PMID 25871473, 2015). "The role of HIF-1α in cancer is well studied, and the role of HIF-2α is increasingly being explored." (PMID 26305551, 2015).
cancer (continued). "It has been shown that HIF-1α and P-glycoprotein levels are positively correlated with each other and their overexpression facilitates multidrug resistance in cancer." (PMID 25714015, 2015). "The HIF-1α complex acts as a transcription factor for many target genes in several aspects of cancer progression including angiogenesis, glucose metabolism, cell proliferation, and apoptosis." (PMID 26612965, 2015). "One study has shown that HIF1α can drive glycolysis and lipogenesis in cancer cells also under normoxic conditions." (PMID 26440364, 2015). "To investigate the effect of HIF-1α on cancer cell invasion of SCC-15 cells in vitro, we used the transwell assay." (PMID 25816356, 2015). "miR-17 and -20a were also included in the validation study as positive controls for they were previously reported to be the strongest regulators of HIF-1α in cancer pathogenesis." (PMID 26030758, 2015). "Mutant phenotypes of TWIST- and HIF1α-null mice exhibit similarities, including cancer progression and metastasis." (PMID 26196741, 2015). "A gene encoding glycoprotein ABC-Ts, MDR1, which confers multidrug resistance on a variety of cancer cells, is a direct HIF-1α-target." (PMID 26210994, 2015). "Interaction of HIF-1α and Notch3, which is required for the expression of the hypoxia-responsive gene Carbonic Anhydrase 9, is a potential target for cancer/stem cell therapy." (PMID 25749383, 2015). "In this work we have shown that REST reduces HIF-1α expression and glycolysis in hypoxia, two promising targets for cancer therapy." (PMID 26647819, 2015). "In this context, the topo II-targeting effects revealed by our present study raised the notion that Q6 exerted a dual mode of action to exploit HIF-1α and topo II simultaneously, thus achieved a superior anti-cancer activity in hypoxic cancer cells." (PMID 26649750, 2015). "The role of the HIFs in cancer progression has long been appreciated due to their ability to promote angiogenesis through one of the principally identified HIF-1α target genes, VEGFA." (PMID 25625467, 2015). "Hypoxia-inducible factor-1α (HIF-1α) is a transcription factor that triggers adaptive responses upon low oxygen conditions and plays a crucial role in cancer metabolism and therapy resistance." (PMID 26469226, 2015). "Taking advantage of a monoclonal antibody neutralizing extracellular S1P (sphingomab), we report that inhibition of S1P extracellular signaling blocks HIF-1α accumulation and activity in several cancer cell models exposed to hypoxia." (PMID 25915662, 2015). "The various HIF-1α expression patterns have different prognostic implications in certain types of cancer." (PMID 25789026, 2015). "HIF-1α is overexpressed in cancer, its expression level is correlated with patient mortality and it plays an important role in human cancer cell invasion and metastasis." (PMID 25742790, 2015). "Radiation-induced HIF-1α expression has been shown to be highly relevant to the malignancy of cancer cells." (PMID 25843954, 2015). "In the current study, we selected auraptene as a candidate modulator of energy metabolism in RCC4 cells through direct targeting of HIF-1α and mitochondrial respiration, examining its suppressive effects on cancer progression." (PMID 26474388, 2015). "Hypoxia inducible factor 1α (HIF1A), is a transcription factor that has major impacts in the process of development and progression of cancers." (PMID 26715988, 2015). "Adenosine was reported to modulate proliferation of cancer cells by a hypoxia-inducible factor1α (HIF-1α)-dependent mechanism." (PMID 26228921, 2015). "HRE and Sp1 sites were found to collaborate to enhance the promoter activity of these genes in a HIF-1α-dependent manner in several types of cancer cell exposed to hypoxia or hypoxia mimetic stimuli." (PMID 26703734, 2015).
cancer (continued). "Accordingly, it has been described that Hif-1α is upregulated in cancer cells, activating signaling pathways that will lead to an increase of PHDK1, PKM1/2 and HEXOKINASE II expression in order to promote a high rate of glycolysis." (PMID 26147621, 2015). "Hypoxia, through activation of hypoxia inducible factors (HIF), especially HIF-1α, regulates a myriad of genes leading to adaptive and genetic changes in the cancer cells resulting in survival advantages." (PMID 26501874, 2015). "Initially, we investigated the protein levels of HIF-1α in response to hypoxic stimulation in these human cancer cell lines." (PMID 25467539, 2014). "The genetic silencing of HIF-1α not only reversed IMQ-induced aerobic glycolysis but also sensitized cancer cells to IMQ-induced apoptosis, as a result of rapid ATP depletion and decreased Mcl-1 levels." (PMID 24658058, 2014). "As a consequence, the understanding of the mechanisms driving the accumulation and degradation of HiF-1α is crucial to identify new targets for anti-cancer therapies." (PMID 25338163, 2014). "The antagonistic modulation of HIF-1α by 15-LO1 versus COX-2 would be an excellent experimental model for investigating the modulation of fatty acid metabolism on cancer development and progression." (PMID 24668884, 2014). "HIF-1α mediates the adaptation of cancer cells to hypoxic environments by controlling expression of hundreds of genes, including vascular endothelial growth factor (VEGF)." (PMID 24988190, 2014). "Multiple reports have documented that HIF1α plays an important role in the glycolytic process characterized by malignant tumors." (PMID 25103363, 2014). "It was suggested that SDHB silencing up-regulated HIF-1α via activation of AMPKα in cancers in accordance with the aerobic glycolysis (Warburg effect)." (PMID 25491408, 2014). "Hypoxia induces an EMT-like phenotype in cancer cells, and HIF-1α regulates the expression of Twist1 by binding directly to the hypoxia-response element (HRE) in the proximal promoter of Twist1." (PMID 25200065, 2014). "Recent studies have also argued for a resistance-mediating effect of HIF-1α, at least in some human cancers." (PMID 24901645, 2014). "Together, these results demonstrated the preferential uptake of NIR dyes by canine and human cancer cells and tissues via the HIF-1α/OATPs signaling axis, which provides insights into future application of these dyes for cancer detection and treatment." (PMID 25361418, 2014). "Treating cancer cells with HIF-1α stabilizers activated HIF-1α downstream target genes, induced OATP superfamily gene expression and enhanced cellular uptake and retention of NIR dyes." (PMID 25361418, 2014). "Hypoxia-inducible factor 1 alpha (HIF-1α) plays a key role in the effects of hypoxia in cancer cells." (PMID 25089613, 2014). "HIF-1β is constitutively active in most cells, whereas HIF-1α is inducible and is characteristically overexpressed in cancer cells during hypoxic conditions." (PMID 25140303, 2014). "We previously engineered a switchable prodrug-activating enzyme that selectively kills human cancer cells accumulating the cancer marker hypoxia-inducible factor-1α (HIF-1α)." (PMID 25426963, 2014). "The vascular endothelial growth factor, cyclooxygenase-2 and isocitrate dehydrogenase-2 were also found to be involved in the regulation of HIF-1α signaling pathway for cancer angiogenesis, invasiveness and metastasis." (PMID 25377659, 2014). "Mutations in SDH or FH are found in cancers and cause succinate or fumarate to accumulate and compete with α-KG for PHD binding, thereby inhibiting PHD and stabilizing HIF-1α." (PMID 25420025, 2014). "Second, we demonstrated that 17-AAG effectively blunted the IMQ induced STAT3 phosphorylation and HIF-1α protein accumulation in cancer cell lines." (PMID 24658058, 2014). "Immunohistochemical studies revealed that many cancers are characterized by overexpression of HIF-1α as compared to normal tissues." (PMID 24745019, 2014).